RNU6-861P (RNA, U6 small nuclear 861, pseudogene)
Gene: Small nuclear RNA gene on chromosome 6 (129,436,875 to 129,436,980, reverse strand). Ensembl gene ENSG00000252554.
Homologues: Orthologues: chimpanzee U6 (98% identical), dog U6 (70% identical), mouse Gm22321 (60% identical). Paralogues in human: RNU6-199P (74% identical), RNU6-1029P (73% identical), RNU6-1048P (73% identical), RNU6-1152P (73% identical), RNU6-140P (72% identical), RNU6-536P (72% identical), RNU6-854P (72% identical), RNU6-1060P (71% identical), RNU6-116P (71% identical), RNU6-19P (71% identical), RNU6-211P (71% identical), RNU6-266P (71% identical), and 1286 more.